WASHC5 (WASH complex subunit 5)
Description:
Acts as a component of the WASH core complex that functions as a nucleation-promoting factor (NPF) at the surface of endosomes, where it recruits and activates the Arp2/3 complex to induce actin polymerization, playing a key role in the fission of tubules that serve as transport intermediates during endosome sorting. May be involved in axonal outgrowth. Involved in cellular localization of ADRB2. Involved in cellular trafficking of BLOC-1 complex cargos such as ATP7A and VAMP7.
Synonyms: KIAA0196; RTSC; RTSC1; SPG8
Tractability: PROTAC: ubiquitination databases record sites on it.
Gene: Protein-coding gene on chromosome 8 (125,024,260 to 125,091,819, reverse strand). Ensembl gene ENSG00000164961.
Subcellular location: Cytoplasm, cytosol; Endoplasmic reticulum; Early endosome
Subcellular location (Human Protein Atlas): Cytosol; Basal body; Centrosome; Cytokinetic bridge; Mitotic spindle; Primary cilium
Gene Ontology:
Molecular function: protein binding
Biological process: endosomal transport; actin filament polymerization; endosome fission; endosome organization; regulation of actin nucleation; regulation of Arp2/3 complex-mediated actin nucleation; meiotic spindle assembly; oocyte maturation; polar body extrusion after meiotic divisions; positive regulation of neuron projection development
Cellular component: cytosol; early endosome; endoplasmic reticulum; endosome; WASH complex; early endosome membrane; neuronal cell body
Genetic constraint (gnomAD): Loss-of-function variants: 66 observed, 102.29 expected, observed/expected ratio (o/e) 0.65, 90% interval 0.53 to 0.79. The upper end of that interval is the gene's LOEUF score, 0.79, which puts it in group 3 of 6, group 1 being the genes least tolerant of losing a copy. Missense variants: 895 observed, 1,127.1 expected, observed/expected ratio (o/e) 0.79, 90% interval 0.75 to 0.84. Synonymous variants: 364 observed, 405.77 expected, observed/expected ratio (o/e) 0.9, 90% interval 0.82 to 0.98.
Gene-disease validity (ClinGen):
ClinGen rates the evidence that WASHC5 causes each of these diseases.
hereditary spastic paraplegia 8 (autosomal dominant): Moderate.
Ritscher-Schinzel syndrome 1 (autosomal recessive): Limited.
Homologues: Orthologues: chimpanzee WASHC5 (100% identical), macaque WASHC5 (99% identical), dog WASHC5 (99% identical), pig WASHC5 (98% identical), rabbit WASHC5 (97% identical), guinea pig WASHC5 (97% identical), mouse Washc5 (96% identical), rat Washc5 (94% identical), tropical clawed frog washc5 (89% identical), zebrafish washc5 (77% identical), Drosophila melanogaster Strump (45% identical), Caenorhabditis elegans T05E7.3 (22% identical).
Diseases named in the same sentence as WASHC5 in open-access papers:
WASHC5 is named in the same sentence as 23 diseases in open-access papers, as found by Europe PMC text mining. Sharing a sentence is not in itself a finding about the gene and the disease. The quoted sentences say what the papers report.
Ritscher-Schinzel syndrome (6 papers, 2015 to 2024). "Ritscher-Schinzel syndrome is a developmental disorder characterized by abnormal craniofacial, cerebellar, and cardiovascular malformations, classically associated with WASHC5 and CCDC22 but more recently with VPS35L and DPYSL5 being implicated as well." (PMID 39282277, 2024). "WASHC5 has been implicated with Ritscher-Schinzel syndrome under a recessive model in an isolated community, with CHD as one of the main clinical features." (PMID 32349777, 2020). "The Retriever subunit VPS35L is the third responsible gene for Ritscher-Schinzel syndrome (RSS) after WASHC5 and CCDC22." (PMID 36113987, 2023).
Spastic paraplegia (2 papers, 2014 to 2021). Complete loss of the ability to move the lower limbs accompanied by spasticity of the lower limbs. "The WASHC5 variant (NP_001317538.1:p.(Asp254Gly)) is predicted to be deleterious, is novel and it is located in the spectrin‐like repeat domain, thus, we cannot rule out a pathological role for this mutation for a spastic paraplegia phenotype, which usually has on onset in adult life." (PMID 33476483, 2021).
Dysarthria (1 paper, 2019). Dysarthric speech is a general description referring to a neurological speech disorder characterized by poor articulation. "The male proband SPG0403, with WASHC5 c.647C>T (p.Pro216Leu), presented a complex HSP with dysarthria." (PMID 30778698, 2019).
focal dystonia (1 paper, 2022). A dystonia that is localized to a specific part of the body. "The TOR1A, KMT2B, or WASHC5 mutations were identified as causative gene in three patients with childhood-onset focal dystonia." (PMID 35719373, 2022).
gastric cancer (1 paper, 2021). A primary or metastatic malignant neoplasm involving the stomach. "For instance, the copy number alteration of WASHC5 (also known as KIAA0196) frequently occurred in gastric cancer patients, which cannot be discovered using traditional methods based on significant mutations." (PMID 33902514, 2021).
WASHC5 also shares sentences with these, for which no sentence is quoted: hereditary spastic paraplegia (5 papers); - tumors (2); Ataxia (2); intellectual disabilities (2); prostate carcinoma (2); Arrhythmia (1); Autosomal dominant spastic paraplegia type 8 (1); brain malformations (1); breast carcinoma (1); cardiomyopathy (1); Dystonia (1); epilepsy (1); hippocampal atrophy (1); hypercholesterolaemia (1); Myoclonus (1); neurodegenerative disease (1); Tremor (1); unspecified (1).